CALB1 (calbindin 1)
Diseases named in the same sentence as CALB1 in open-access papers (continued):
Sharing a sentence is not in itself a finding about the gene and the disease.
cancer (12 papers, 2017 to 2025). A tumor composed of atypical neoplastic, often pleomorphic cells that invade other tissues. "The sequential genes upregulated during the progression from cancer stage 1 to 4 are CALB1, TPD52L1 and ITGB8." (PMID 39149248, 2024). "In contrast, in CALB1-expressing tumors, transcription of the same mediators was minimal in cancer cells and instead was found in myeloid cells (CXCL2, CXCL8) and/or tumor-associated fibroblasts (CXCL5, CXCL6)." (PMID 37192000, 2023). "Many of the upregulated genes, i.e., PARP8, ATP6, V1G3, NANOGNB, and CALB1, have been reported to be upregulated in various cancer cells." (PMID 36230929, 2022). "Cancer-specific HERVH-driven expression of CALB1 predicts LUSC survival." (PMID 37192000, 2023). "Thus, cancer cells were the main producers of CXCL1, CXCL2, and CXCL8, but cancer cell–intrinsic production of these chemokines was prevented by CALB1 expression." (PMID 37192000, 2023). "Moreover, expression of CALB1 in cancer cells exhibited a highly significant inverse correlation with cancer cell–intrinsic expression of CXCL1, CXCL2, and CXCL8 and a positive correlation with CCL26 expression, which did not, however, reach statistical significance (P = 0.057)." (PMID 37192000, 2023). "These included CALB1, AURKB, SEPT14, and the histone-coding gene HIST1H1B and downregulated ADH1B and C7 in 11 cancer types." (PMID 38763334, 2024). "Given the growth defects of CALB1-deficient LUSC cell lines, autocrine CXCL8 signaling driving cancer cell–intrinsic growth is unlikely to compensate for this proliferative disadvantage or to explain the worse prognosis of CALB1-negative tumors." (PMID 37192000, 2023). "In established carcinomas, CALB1-negative cancer cells became the dominant source of CXCL8, correlating with neutrophil infiltration and worse prognosis." (PMID 37192000, 2023). "In biopsies lacking CALB1 expression, cancer cells not only transcribed CXCL1, CXCL2, CXCL8, and other immune mediators; they were also the predominant source." (PMID 37192000, 2023). "Nevertheless, paracrine CXCL8 growth signals on nonsenescent cancer cells or angiogenic signals on endothelial cells may indeed contribute to the poorer outcome of CALB1-negative tumors." (PMID 37192000, 2023). "Exceptions to this pattern were IL1B, which was transcribed predominantly by myeloid cells irrespective of the CALB1 status of the tumor, and CCL26, which was transcribed predominantly by CALB1-expressing cancer cells." (PMID 37192000, 2023).
tumor (9 papers, 2010 to 2025). "This phenotype was recapitulated in LK-2 tumors that developed in Rag2–/–Il2rg–/–Cd47–/– recipient mice, where a significantly higher proportion of parental LK-2 than CALB1-deficient LK-2 2B7 tumor cells stained positive for p63, a marker for squamous epithelial differentiation encoded by TP63." (PMID 37192000, 2023). "Firstly, at a wide level, the overexpression of CALB1 was shown to suppress apoptosis in the tumoral cells, presumably resulting in a worse outcome of neoplastic diseases." (PMID 38928369, 2024). "According to the Expression Atlas, the hypoxia-associated molecules CALB1, DDAH1, GAP43 and GPR37, as well as the tumor markers ART3, ENOL2 and FMOD and the tumor promoter NTNG1, are typically expressed in hematopoietic stem cells." (PMID 32466393, 2020). "Loss of CALB1 expression in HARA 3D5 cells significantly reduced tumor burden in the livers, but not in the lungs of recipients that did develop tumors." (PMID 37192000, 2023). "Using MRM‐based quantification, it was found that VCAM1, CALB1, CSPG4, and VTDB also dynamically changed with tumor progression." (PMID 28980450, 2017).
neurodegenerative disease (7 papers, 2018 to 2025). A disorder of the central nervous system characterized by gradual and progressive loss of neural tissue and neurologic function. "Thus, it may be plausible to speculate that decreased CALB1 expression during aging and altered Ca2+ signaling could result in increased risk of various neurodegenerative diseases." (PMID 38428408, 2024). "Calb1 has been reported to affect the long-term enhanced activity and learning function of the hippocampus and plays a positive role in promoting neurodegenerative diseases." (PMID 39635132, 2024). "These enriched TFs displayed maximum interactions with their target genes (GPR50, ABCC9, ZNF667 and CALB1) and could prove relevant to several neurodegenerative diseases." (PMID 32967368, 2020).
CALB1 also shares sentences with these, for which no sentence is quoted: Hypercalciuria (4 papers); chronic kidney disease (3); dementia (3); cerebellar ataxia (2); dental caries (2); depression (2); Diabetes (2); epilepsy (2); Huntington disease (2); Hypertension (2); infection (2); mood disorder (2); neurological diseases (2); Parkinson’s (2); tuberous sclerosis (2); Type 1 diabetes (2); autism (1); bipolar disorder (1); bladder cancer (1); brain ischemia (1); cognitive disorder (1); colorectal cancer (1); congestive heart failure (1); COVID-19 (1); Ewing sarcoma (1); glioblastoma (1); Gliosis (1); hearing loss (1); Hypomagnesemia (1); ischemia (1).
A further 21 diseases each share a sentence with CALB1 in 1 paper.